ADORA1 (adenosine A1 receptor)
Diseases named in the same sentence as ADORA1 in open-access papers (continued):
Sharing a sentence is not in itself a finding about the gene and the disease.
ischemic stroke (2 papers, 2021). A stroke disorder caused by obstruction of blood flow to the brain, due to thrombotic (local blood clot formation) or embolic (due to a blood clot or other material traveling from another site) event. "Taken together, OPRM1 and ADORA1 may be associated with the susceptibility of ischemic stroke through the inflammatory pathway." (PMID 34483854, 2021). "Thus, we speculated that KCNQ1OT1, SND1-IT1, NAPA-AS1, and LINC01001 may interact with miR-24-3p and facilitate the regulation of LPAR3 and ADORA1 in ischemic stroke." (PMID 34483854, 2021). "Regulatory axis, such as SND1-IT1/NAPA-AS1/LINC01001-miR-24-3p-LPAR3/ADORA1 and LUCAT1/ASAP1-IT2-miR-93-3p-GPR17 may play important roles in the progression of ischemic stroke." (PMID 34483854, 2021). "lncRNA-miRNA-mRNA regulatory axis such as SND1-IT1/NAPA-AS1/LINC01001-miR-24-3p-LPAR3/ADORA1 and LUCAT1/ASAP1-IT2-miR-93-3p-GPR17 may play important roles in the progression of ischemic stroke." (PMID 34483854, 2021). "In conclusion, LPAR3, ADORA1, GPR17, and OPRM1 may serve as therapeutic targets of ischemic stroke." (PMID 34483854, 2021). "LPAR3, ADORA1, GPR17, and OPRM1 may serve as therapeutic targets of ischemic stroke." (PMID 34483854, 2021).
tauopathy (2 papers, 2023 to 2024). Neurodegenerative disorders involving deposition of abnormal tau protein isoforms (tau proteins) in neurons and glial cells in the brain. "In this regard, the downregulation of Adora1 (encoding adenosine receptor 1) after MSUT2 KO is noteworthy, as the literature suggests a potential linkage of Adora1 with tauopathy, as well as an involvement in neuronal endocytosis." (PMID 38472475, 2024). "Using the mouse model of tauopathy TauΔK, we have previously shown the beneficial effect of the adenosine A1 receptor antagonist rolofylline in TauΔK mice and in organotypic hippocampal slice cultures." (PMID 37298211, 2023). "In the present paper, we assessed the potential beneficial effect of the adenosine A1 receptor antagonist rolofylline in transgenic mouse models of tauopathy." (PMID 37298211, 2023).
Tremor (2 papers, 2021 to 2022). An unintentional, oscillating to-and-fro muscle movement about a joint axis. "A selective adenosine A1 receptor agonist has been shown to significantly reduce extracellular levels of glutamate in VA/VL thalamic nuclei in rats, as well as significantly reduce the amplitude of harmaline-induced tremor." (PMID 35965995, 2022).
alcohol abuse (1 paper, 2012). The use of alcoholic beverages to excess, either on individual occasions ("binge drinking") or as a regular practice. "Our results further suggest therapies that target ADORA1 and/or AMPK may potentially be beneficial in the treatment of alcohol abuse related ARDS." (PMID 22272351, 2012).
anxiety disorder (1 paper, 2015). A category of psychiatric disorders which are characterized by anxious feelings or fear often accompanied by physical symptoms associated with anxiety. "There was also a non-significant trend toward an association between the GG genotype in ADORA1 rs2228079 and non-OCD anxiety disorders." (PMID 26317759, 2015).
attention deficit-hyperactivity disorder (1 paper, 2022). A disorder characterized by a marked pattern of inattention and/or hyperactivity-impulsivity that is inconsistent with developmental level and clearly interferes with functioning in at least two settings (e.g. at home and at school). "Recently, studies have shown the association of adenosine and its receptor (ADORA1, Adenosine A2A Receptor [ADORA2A]) with many CNS disorders such as attention deficit hyperactivity disorder (ADHD) and Gilles de la Tourette syndrome." (PMID 35628334, 2022).
colorectal cancer (1 paper, 2020). A primary or metastatic malignant neoplasm that affects the colon or rectum. "Metformin treatment appreciably upregulates ADORA1 expression in colorectal cancer cells." (PMID 32399389, 2020). "The ADORA1-mediated growth inhibition and apoptosis induced by metformin are AMPK-mTOR pathway dependent in human colorectal cancer cells." (PMID 32399389, 2020).
diabetic nephropathy (1 paper, 2021). "We previously observed that adenosine A1 receptor (A1AR) had a protective role in proximal tubular megalin loss associated with albuminuria in diabetic nephropathy (DN)." (PMID 34671682, 2021).
endothelial dysfunction (1 paper, 2016). In vascular diseases, endothelial dysfunction is a systemic pathological state of the endothelium (the inner lining of blood vessels) and can be broadly defined as an imbalance between vasodilating and vasoconstricting substances produced by (or acting on) the endothelium. "Variants in adenosine A1 receptor (ADORA1) were associated with endothelial dysfunction in the entire cohort, whereas variants in adenosine A3 receptor (ADORA3) and lipoprotein(a) (LPA) had the strongest associations with increased risk of endothelial dysfunction in women only." (PMID 27932996, 2016).
Gilles de la Tourette Syndrome (1 paper, 2015). "Genotypic and allelic association analysis of ADORA1 rs2228079 and ADORA2A rs5751876 variants with co-morbid disorders in patients with Gilles de la Tourette syndrome." (PMID 26317759, 2015).
Glucose intolerance (1 paper, 2023). Glucose intolerance (GI) can be defined as dysglycemia that comprises both prediabetes and diabetes. "ADORA1 encodes an adenosine receptor that suppresses lipolysis in adipocytes, and loss of the receptor leads to glucose intolerance in obese mice." (PMID 37961277, 2023).
hearing loss (1 paper, 2017). "In this respect, G-protein coupled receptors, such as adenosine A1 receptor and cannabinoid 2 receptors, have shown efficacy in the treatment of hearing loss in experimental animals by increasing ROS scavenging, suppressing ROS generation, or by decreasing inflammation." (PMID 29163050, 2017).
hepatoblastoma (1 paper, 2024). Hepatoblastoma (HB) is a malignant hepatic tumor and is the most common pediatric liver cancer. "In detail, we performed cell-line drug response and viability assays on the human HEPG2 hepatoblastoma cell line for CGS-15943, an ADORA2A and ADORA1 inhibitor, which is reported to act against multiple adenosine receptors, and MRS-1220, an ADORA3 and ADORA2B inhibitor." (PMID 38723607, 2024).
Hyperglycemia (1 paper, 2013). An increased concentration of glucose in the blood. "Hyperglycemia has no direct effect in blocking adenosine A1 receptor (A1R) activation, which is a well-characterized mediator of ischemic preconditioning." (PMID 24371503, 2013).
hyperthyroidism (1 paper, 2013). Overactivity of the thyroid gland resulting in overproduction of thyroid hormone and increased metabolic rate. "Therefore, in a previous study we investigated the consequences of the administration of a specific agonist of adenosine A1 receptor on behavioral and biochemical parameters after hyperthyroidism induction." (PMID 23956925, 2013).
infarct (1 paper, 2011). "Exogenous ADORA1 and ADORA3 agonists reduced cardiac infarct size and improved functional recovery in isolated heart models." (PMID 21603615, 2011).
intracerebral hemorrhage (1 paper, 2025). A cerebrovascular disorder characterized by bleeding into one or both cerebral hemispheres including the basal ganglia and the cerebral cortex. "In a study with an animal model for intracerebral hemorrhage, it was seen that the neuroprotective action of RSV was linked to the adenosine A1 receptor." (PMID 40732240, 2025).
latent infection (1 paper, 2019). "Adenosine binding to ADORA1 protein decreased intracellular cAMP levels, thus depressing HSV-1 latent infection." (PMID 30875759, 2019).
Leukoencephalopathy (1 paper, 2025). This term describes abnormality of the white matter of the cerebrum resulting from damage to the myelin sheaths of nerve cells. "One study demonstrated that polymorphisms in the ADORA1 adenosine A2A receptor and ADORA2A gene were associated with methotrexate-related leukoencephalopathy in children with ALL." (PMID 41009999, 2025).
liver cirrhosis (1 paper, 2011). "Further studies will have to establish whether adenosine A1 receptor antagonists are clinically beneficial at different stages of liver cirrhosis." (PMID 21423778, 2011).
liver disease (1 paper, 2022). "Previous studies showed that CD73 and adenosine A1 receptor (A1R) were important in alcohol-related liver disease, however the exact mechanism is unclear." (PMID 35784730, 2022).
lymph node metastasis (1 paper, 2021). "And ADORA1 expression was positively correlated with pathological stage (p = 0.00001, r = 0.632) and lymph node metastasis (p = 0.01, r = 0.64) in Shanghai cohort." (PMID 34093805, 2021). "And ADORA1 was positively correlated with lymph node metastasis as well as pathological stage in PTC." (PMID 34093805, 2021). "As shown by the immunohistochemistry results, ADORA1 was overexpressed in PTC and had positive correlations with pathological stage and lymph node metastasis in Shanghai cohort." (PMID 34093805, 2021).
medulloblastoma (1 paper, 2013). A malignant, invasive embryonal neoplasm arising from the cerebellum. "ADORA1 was under-expressed in the Non-WNT/SHH group (0.088-fold, p = 0.03), again suggesting that loss of ADORA1 activity may play a role in the pathogenesis of a Non-WNT/SHH medulloblastoma tumors, especially those seen in Cluster “E”." (PMID 24252460, 2013).
mental disorder (1 paper, 2018). A disease that has its basis in the disruption of mental process. "Specially, the crucial neuroactive ligand-receptor interaction pathway has been applied into the analysis of mental disorders, which is regulated by 25 potential targets (ADORA1, ADORA2A, ADORA3, etc.)." (PMID 30127739, 2018).
migraine (1 paper, 2022). "We suggest that the adenosine A1 receptor and adenosine A2A receptor could be potential targets for migraine treatment." (PMID 35382738, 2022).
myocardial hypertrophy (1 paper, 2020). "Last, Adora1 agonist rescued heart dysfunction and cardiac hypertrophy in zfp91 loss mice after TAC." (PMID 32677376, 2020). "Recently, Devaux's team found that Adora1 agonist can reduce myocardial hypertrophy, interstitial fibrosis and oxidative stress in mice induced by phenylephrine stimulation." (PMID 32677376, 2020).
myocardial ischemia (1 paper, 2011). A disorder of cardiac function caused by insufficient blood flow to the muscle tissue of the heart. "The expression of the genes ADORA1, involved in myocardial ischemia and dilated cardiomyopathy, and PTGDS, recently associated with the progression of atherosclerosis were significantly up-regulated in EAT." (PMID 21603615, 2011). "More specifically, the expression of the adenosine A1 receptor (ADORA1), involved in myocardial ischemia, was significantly up-regulated in EAT." (PMID 21603615, 2011).
Nephropathy (1 paper, 2023). A nonspecific term referring to disease or damage of the kidneys. "The identification of ADORA1 as a key target for T2DM and related complications (e.g., nephropathy) therapy buttresses previous studies (on morusin, kuwanon C, and morusyunnansin) from Morus alba (leaves) and Salvia miltiorhiza through NP and molecular docking analyses." (PMID 38132335, 2023).
nonalcoholic steatohepatitis (1 paper, 2020). "Three genes in particular, ACOT1, ADIPOR2 and ADORA1, are associated with nonalcoholic steatohepatitis." (PMID 32075112, 2020).
Obesity (1 paper, 2022). Accumulation of substantial excess body fat. "Meanwhile, activation of ADORA1 signaling in peripheral tissues facilitates high-fat diet-induced obesity." (PMID 36278175, 2022). "In contrast, activation of ADORA1 in peripheral tissues could facilitate HFD-induced obesity in C57BL/6J mice." (PMID 36278175, 2022).
osteoporosis (1 paper, 2025). A condition of reduced bone mass, with decreased cortical thickness and a decrease in the number and size of the trabeculae of cancellous bone (but normal chemical composition), resulting in increased fracture incidence. "Molecular docking technology further reveals that the two drugs can produce pathological effects by binding to osteoporosis-related genes such as ADORA1 and JAK1." (PMID 40687725, 2025).
papillary thyroid carcinoma (1 paper, 2021). "To illuminate the role of ADORA1 in papillary thyroid cancer, we first evaluated its expression, diagnostic value and prognostic value in patients with PTC." (PMID 34093805, 2021). "Data in the TCGA database and the Oncomine database revealed that mRNA expression of ADORA1 were significantly higher in papillary thyroid cancer tissues than that in normal tissues." (PMID 34093805, 2021). "However, the expression and prognostic value and mechanism of ADORA1 in thyroid papillary carcinoma have not been reported." (PMID 34093805, 2021).
parathyroid adenomas (1 paper, 2013). "ADORA1 showed relatively even expression between the normal parathyroid and the 7 parathyroid adenomas investigated." (PMID 23788688, 2013). "We detected both ADORA1 and ADORA2A at the protein level in normal parathyroid and parathyroid adenomas." (PMID 23788688, 2013). "The expression of ADORA1, ADORA2A, and PTH after 30-minute caffeine treatment of cultured parathyroid adenoma cells was evaluated by qRT-PCR." (PMID 23788688, 2013). "ADORA1 showed an equal expression in normal and parathyroid adenomas, whereas ADORA2A was found to be weak or absent in some parathyroid adenoma samples." (PMID 23788688, 2013).
Parkinson disease (1 paper, 2024). A progressive degenerative disorder of the central nervous system characterized by loss of dopamine producing neurons in the substantia nigra and the presence of Lewy bodies in the substantia nigra and locus coeruleus. "We previously found that chronic adenosine A1 receptor stimulation with N6-Cyclopentyladenosine increased α-synuclein misfolding and neurodegeneration in a novel α-synucleinopathy model, a hallmark of Parkinson’s disease." (PMID 39273333, 2024). "The 18F-labeled dimer remained stable post-injection and distributed in various organs, notably in the brain, suggesting its potential as a Positron Emission Tomography tracer for α-synuclein and adenosine A1 receptor in Parkinson’s disease therapy." (PMID 39273333, 2024).
pituitary tumor (1 paper, 2024). A benign or malignant neoplasm affecting the pituitary gland. "For instance, cordycepin has been found to inhibit PRL secretion in rat pituitary tumor cells (GH3) by inducing the expression of cell surface protein ADORA1 and regulating the activation of p-PI3K, p-AKT, p-ERK1/2, and other proteins." (PMID 39199216, 2024).
status epilepticus (1 paper, 2017). Status epilepticus is defined as a continuous seizure lasting more than 30 min, or two or more seizures without full recovery of consciousness between any of them. "Besides, spontaneous electrographic seizures were observed in the cerebral cortex of inactivated adenosine A1 receptor experimental epileptic mice, and in experimental traumatic brain injury (TBI) animal model, adenosine A1 receptor knockout promoted status epilepticus after TBI." (PMID 28415676, 2017).
synovitis (1 paper, 2025). Inflammation of a synovial membrane. "The results show that the adenosine A1 receptor is involved in the anti-inflammatory effects of medical ozone in carrageenan-induced synovitis in Wistar rats." (PMID 40508064, 2025).
thyroid cancer (1 paper, 2021). "The results revealed that high expression of ADORA1 (HR=2.87, 95% CI: 1.25-6.6, and p=0.0094) was associated with a worse disease free survival in the thyroid carcinoma patients while high expression of ADORA1 (HR=0.36, 95% CI: 0.14-0.97, and p=0.035) was associated with a longer overall survival." (PMID 34093805, 2021). "The prognostic value of ADORA1 mRNA expression levels in thyroid cancer was conducted utilising Kaplan-Meier Plotter." (PMID 34093805, 2021). "Then, we analyzed the expression of ADORA1 with the tumor stage, patients' age, patients' race, patients' gender and nodal metastasis status for thyroid carcinoma." (PMID 34093805, 2021).
Tics (1 paper, 2015). Repeated, individually recognizable, intermittent movements or movement fragments that are almost always briefly suppressible and are usually associated with awareness of an urge to perform the movement. "We hypothesize that the functional imbalance between the direct and indirect pathways dependent on the activity of adenosine receptors due to abnormal expression of ADORA1 and ADORA2A genes could be responsible for the appearance of tics." (PMID 26317759, 2015).
Type 1 diabetes (1 paper, 2025). "Similarly, reduced expression of the adenosine A1 receptor (Adora1) led to islet inflammation in a mouse model of Type 1 diabetes." (PMID 40951793, 2025).
Ventricular arrhythmia (1 paper, 2015). "Sitagliptin protects ventricular arrhythmias by attenuating sympathetic innervation via adenosine A1 receptor and xanthine oxidase-dependent pathways, which converge through the attenuated formation of superoxide in the non-diabetic infarcted rats." (PMID 25388908, 2015).